ALDH1A3 (aldehyde dehydrogenase 1 family member A3)
Diseases named in the same sentence as ALDH1A3 in open-access papers (continued):
Sharing a sentence is not in itself a finding about the gene and the disease.
cataract (2 papers, 2020 to 2023). Partial or complete opacity of the crystalline lens of one or both eyes that decreases visual acuity and eventually results in blindness. "Third, miR-204 downregulation in age-related cataract and PCO suggest that miR-204 targets genes involved in EMT (e.g., αSMA) and oxidative stress (e.g., ALDH1A3), whereas miR-204 downregulation in congenital cataract implicated targeting of Meis2." (PMID 32070426, 2020).
gastric tumors (2 papers, 2019 to 2024). "In addition, the resistance and recurrence upon treatment with chemotherapy were strongly associated with the enrichment of CD44 and ALDH1A3 CSC markers in the FOLFOX-treated tumor organoids (tumoroids) derived from Apc1638N mouse gastric tumors." (PMID 30965636, 2019). "A potential contribution of chemotherapy to the activation of CSCs was shown by the enrichment of CD44 and ALDH1A3 in the tumoroids derived from gastric tumor tissues from Apc1638N mice, which reduced their size upon FOLFOX treatment." (PMID 30965636, 2019). "In this animal model, increases of CD44 and ALDH1A3 CSC markers were also observed in gastric tumors compared with their levels in adjacent normal tissue." (PMID 30965636, 2019). "Taken together, these observations indicate that BET inhibitors, which potentially interfere with BRD4 recruitment to the ALDH1A3 promoter, decrease DTP cell survival and enhance chemotherapeutic efficacy against gastric tumors in vivo." (PMID 38669046, 2024). "The efficacy test of the drugs using gastric tumor organoids of Apc1638N mice showed that the CD44 and ALDH1A3 cancer stem cell markers were induced by FOLFOX, but not by KYA1797K." (PMID 30965636, 2019).
hepatocellular carcinoma (2 papers, 2024). A malignant tumor that arises from hepatocytes. "For instance, exosomes containing long non-coding RNA derived from TAMs activate glycolysis in hepatocellular carcinoma (HCC) via the miR-548 s/ALDH1A3 pathway, demonstrating that metabolic reprogramming is an essential mechanism through which exosomes promote malignant proliferation." (PMID 38195554, 2024).
Hyperglycemia (2 papers, 2020 to 2021). An increased concentration of glucose in the blood. "The most striking change was however revealed by the drastic reduction in the expression of Aldh1a3 and Serpina7 in SHD-STZ + Tx islets, thereby evidencing the major involvement of hyperglycemia in β-cell dedifferentiation." (PMID 32999405, 2020).
multiple myeloma (2 papers, 2014). "Our recent studies showed that deficiency in Aldh1a1, but not in Aldh1a2 and Aldh1a3, is the characteristic feature of B cell cancers in humans, especially multiple myeloma (MM)." (PMID 24594504, 2014).
osteosarcoma (2 papers, 2021 to 2023). A usually aggressive malignant bone-forming mesenchymal neoplasm, predominantly affecting adolescents and young adults. "In osteosarcoma, tumorigenicity was associated with ALDH1A3 expression." (PMID 36672441, 2023). "Some studies have reported miR-487b-3p as a tumor suppressor that inhibits osteosarcoma chemoresistance and metastasis by targeting ALDH1A3." (PMID 35008541, 2021). "In osteosarcoma, miR-487b-3p targets ALDH1A3, leading to chemosensitivity and reduced CSCs." (PMID 36672441, 2023).
prostate tumor (2 papers, 2015 to 2023). "Hence, ALDH1A3 was found to be up-regulated in prostate tumors and the expression of this protein is inversely correlated with the expression of the miRNA." (PMID 25969992, 2015).
albinism (1 paper, 2020). A congenital disorder characterized by partial or complete absence of melanin pigment in the eyes, hair, or skin. "The genes identified for MAC were KMT2D, MAB2IL2, ALDH1A3; ASDA were KERA, PAX6, MYOC, TGFBI, and SLC4A11; congenital cataract were CRYBB2, EPHA2, HSF4 and BCOR; infantile nystagmus were CACNA1A and FRMD7; and albinism were OCA2, GPR143, HPS6 and SLC38A8." (PMID 32830442, 2020).
atherosclerosis (1 paper, 2025). A disease characterized by the build-up of fatty material and calcium deposition in the arterial wall resulting in partial or complete occlusion of the arterial lumen. "PPARγ plays a key role in inhibiting atherosclerosis, which suggests that ALDH1A3 is related to atherosclerosis by suppressing ferroptosis and enhancing PPARγ expression." (PMID 40176913, 2025). "Taken together, the downstream genes of ARL4C, including ABCA1, ALDH1A3, ARF6, ENHO, FLNA, LRP6, OSBPL5, Snail2, and SOX2 play an important role in atherosclerosis." (PMID 40176913, 2025).
basal cell carcinoma (1 paper, 2024). A carcinoma involving the basal cells. "Microarray analysis also revealed an upregulation in ALDH1A3 and NR4A3, which are genes that have since been identified as being commonly recognized biomarkers for carcinoma-associated fibroblasts (CAFs) in skin disorders including basal cell carcinoma and systemic sclerosis." (PMID 38948860, 2024).
bladder cancer (1 paper, 2023). "In contrast, in bladder cancer, ALDH1A3 hypermethylation was associated with progressive disease and recurrence in non-muscle invasive bladder cancer." (PMID 36672441, 2023).
Blepharophimosis (1 paper, 2023). A fixed reduction in the vertical distance between the upper and lower eyelids with short palpebral fissures. "The facial dysmorphic features described in individuals with ALDH1A3 variants include bilateral small palpebral fissures or blepharophimosis, which is often seen in individuals with small eye sockets secondary to severe A/M, irrespective of the genetic cause." (PMID 36997679, 2023).
carcinoma in situ (1 paper, 2025). "As expected, Aldh1a3 overexpression led to increased expression of Fosl1 and Fosb and enhanced Jnk pathway activity, correlating with carcinoma in situ formation and a significant stromal reaction compared to control mice." (PMID 40781158, 2025).
cervical cancer (1 paper, 2015). A primary or metastatic malignant neoplasm involving the cervix. "From these results, the expression of the CAMK2N1, ALDH1A3 and PPP1R3C genes are were shown to be suppressed in cervical cancers by DNA methylation." (PMID 25789025, 2015). "However, to the best of our knowledge, there have been no studies regarding the methylation of ALDH1A3 in cervical cancer." (PMID 25789025, 2015).
choriocarcinoma (1 paper, 2019). An aggressive malignant tumor arising from trophoblastic cells. "The highest frequency of the ALDH1A3 expression was found in teratomas (77.8%), with decreasing trend in GCNIS (74.6%), embryonal carcinomas (71.0%), in choriocarcinomas (63.6%), yolk sac tumors (46.7%) and, at least, in seminomas (42.0%)." (PMID 31443351, 2019).
cleft palate (1 paper, 2011). Cleft palate is a fissure type embryopathy that affects the soft and hard palate to varying degrees. "We also excluded the possibility that TCDD acts through binding to, and activating, RARG because ablation of Aldh1a3 was sufficient to prevent TCDD-induced cleft palate." (PMID 21807577, 2011).
diabetic retinopathy (1 paper, 2022). "For example, genes such as Aldh1a3, Cyp26b1 and Acaa2, without reference regarding anti-diabetic retinopathy function, would be the candidates for our future exploration." (PMID 36557283, 2022).
diffuse gastric adenocarcinoma (1 paper, 2016). An adenocarcinoma arising from the stomach. "Interestingly, for ALDH1A2, ALDH1A3 and ALDH1L1, high mRNA level was found to be significantly correlated to worsen OS in both gastric intestinal type adenocarcinoma and diffuse gastric adenocarcinoma, with the same trend as in all GC patients." (PMID 27015121, 2016).
Fanconi anemia (1 paper, 2019). Fanconi anemia (FA) is a hereditary DNA repair disorder characterized by progressive pancytopenia with bone marrow failure, variable congenital malformations and predisposition to develop hematological or solid tumors. "qRT-PCR data confirmed that the expression of Fanconi anemia-associated genes including BRCA1, BRCA2, PALB2, and RAD51 and cancer-associated genes (ALDH1A3 and IGF1R) was strongly inhibited by FR treatment, as shown by microarray analysis." (PMID 30719229, 2019).
gastric adenocarcinoma (1 paper, 2016). "Consistently, in another dataset with 132 samples from patients with different types of gastric adenocarcinoma, the mRNA level of ALDH1A3 was over 2 up-fold change than in gastric mucosa." (PMID 27015121, 2016).
germ cell tumor (1 paper, 2019). A benign or malignant, gonadal or extragonadal neoplasm that originates from germ cells. "When we analyzed dichotomized ALDH1A3 expression data (absent vs. present), all of the histological subtypes of germ cell tumors exhibited significantly higher expression of the ALDH1A3 compared to normal testicular tissue." (PMID 31443351, 2019).
hearing loss (1 paper, 2019). "Hence, we postulate a molecular link between enhanced ALDH1A3 expression and hearing loss in FKBP14-kEDS patients that warrants further investigation." (PMID 31288483, 2019).
Hypertension (1 paper, 2025). The presence of chronic increased pressure in the systemic arterial system. "While evaluating the role of these genes in hypertension and HPO terms, we did find that the upregulation of proteins ALDH1A3, ARMT1, and CDH2 can be crucial in the treatment." (PMID 40940770, 2025).
insulinoma (1 paper, 2016). "As Foxo1 loss-of-function is associated with increased ALDH1A3 levels, we asked whether Foxo1 regulates ALDH1A3 in MIN6 insulinoma cells." (PMID 27572106, 2016).
invasive breast carcinoma (1 paper, 2016). A carcinoma that infiltrates the breast parenchyma. "In addition, expression of ALDH1A3 was positively associated with grade in ER-positive tumors, as well as positively correlated with tumor staging, rendering ALDH1A3 a candidate biomarker for metastasis in invasive breast cancers." (PMID 26892392, 2016).
lactic acidosis (1 paper, 2025). Metabolic acidosis characterized by the accumulation of lactate in the body. "Additionally, in the KKU-213A CCA cell line, which harbors numerous mtDNA SNVs, prior studies have shown that ALDH1A3 expression significantly rises under lactic acidosis (LA) conditions and correlates with LDHA expression." (PMID 40489465, 2025).
lipidosis (1 paper, 2023). "Decreased expression of Aldh1a3 correlates with hepatic lipidosis and liver fibrosis as well as increased microvascular lipidosis caused by lipid peroxidation, possibly due to an accompanying decrease in β-oxidation." (PMID 37958806, 2023).
lung adenocarcinoma (1 paper, 2023). A carcinoma that arises from the lung and is characterized by the presence of malignant glandular epithelial cells. "Also, the knockdown of ALDH1A3 markedly enhanced the sensitivity of lung adenocarcinoma to cisplatin." (PMID 37954205, 2023).
malignant mesothelioma (1 paper, 2019). A malignant neoplasm of the pleura or peritoneum, arising from mesothelial cells. "ALDH1A3 is highly expressed in CSC from malignant mesothelioma, and the repression of STAT3-NFκB signaling diminishes ALDH1A3 accumulation sensitizing cancer cells to pemetrexed and cisplatin treatments." (PMID 31781251, 2019).
microcephaly (1 paper, 2022). A congenital or acquired developmental disorder in which the circumference of the head is smaller than normal for the person's age and sex. "The results show that under these conditions, ALDH1A3 knockdown induces severe microcephaly in a large proportion of embryos (35.1%)." (PMID 35372345, 2022). "These same cells express aldh1a3, whose knockdown results in microcephaly and abnormal expression of head organizer genes, further supporting an early role for RA signaling and ALDH1A3 in the formation of the head." (PMID 35372345, 2022). "The addition of low amounts of RA to the aldh1a3 CRISPant embryos reduced the extent of severe microcephaly by about a third (to 15.4–16.2%)." (PMID 35372345, 2022). "Whereas, among Cas9 injected control embryos only 8.4% developed severe microcephaly, targeting the aldh1a3 gene with sgR3 resulted in a significant three-fold increase (25%) of embryos with severe microcephaly." (PMID 35372345, 2022). "Then, reduced RA signaling could induce microcephaly by affecting the morphogenetic movements of the aldh1a3-expressing LEM/PCM cells out of the Spemann-Mangold organizer, or by directly affecting the inductive signals from these cells." (PMID 35372345, 2022). "We could show that reducing ALDH1A3 activity induces microcephaly and prevents head formation in a secondary axis induction assay." (PMID 35372345, 2022). "ALDH1A2 knockdown induced a weaker microcephaly suggesting that the ALDH1A3 activity might play a more central role in the induction and formation of the head and aldh1a2 performs a very early function that can be partially compensated by aldh1a3." (PMID 35372345, 2022). "We reduced the expression of ALDH1A3 or ALDH1A2 by MO-mediated knockdown in the endogenous organizer by injecting embryos dorsally with R2MO, R3MO, or coMO, and the extent of induced microcephaly was quantitated." (PMID 35372345, 2022). "We show that aldh1a3 knockdown with antisense morpholino oligonucleotides or by gene targeting with CRISPR/Cas9 efficiently hampers the formation of head structures, resulting in microcephaly in both the endogenous and induced secondary axes." (PMID 35372345, 2022).
nasopharynx squamous cell carcinoma (1 paper, 2021). "Decreased levels of ALDH1A1, ALDH1A2, ALDH1A3, and ALDH1L1 expression were observed in 5 pairwise samples of nasopharynx squamous cell carcinoma (the results are not shown)." (PMID 34680942, 2021).
pleural mesothelioma (1 paper, 2023). A neoplasm that arises from the mesothelial cells of the pleura. "The inhibition of the NF-κB pathway can downregulate the activity of the promoter of ALDH1A3 gene, thus inhibiting the transcription of ALDH1A3 gene in pleural mesothelioma cell lines." (PMID 36980923, 2023). "Other studies have reported that NF-κB inhibitor can downregulate the activity of ALDH1A3 promoter and then inhibit the transcription of ALDH1A3 in pleural mesothelioma cell lines." (PMID 36980923, 2023).
schizophrenia (1 paper, 2013). A major psychotic disorder characterized by abnormalities in the perception or expression of reality. "Seven genes were investigated and involved in the synthesis, degradation and transportation of RA, ALDH1A1, ALDH1A2, ALDH1A3, CYP26A1, CYP26B1, CYP26C1 and Transthyretin (TTR), for their roles in the development of schizophrenia." (PMID 24564241, 2013).
squamous cell carcinoma (1 paper, 2016). A carcinoma arising from squamous epithelial cells. "MMP7 and ALDH1A3, that are stem cell markers for squamous cell carcinoma, were not expressed in neither treated nor untreated tumors." (PMID 27716314, 2016).
steatosis (1 paper, 2018). Increased lipid within the cytoplasm of cells. "As expected from previous works, steatosis per se down-regulated the expression of several phase I and II XMEs of HepaRG cells, with some exceptions such as CYP2E1, ALDH1A3 and GSTM2P1 whose expression was increased." (PMID 29654281, 2018).
testicular tumors (1 paper, 2019). "This study showed for the first time significant differences in the ALDH1A3 expression in different histological subtypes of testicular tumors compared to normal testicular tissue." (PMID 31443351, 2019). "In order to verify the clinical relevance of these findings, we analyzed 216 patient samples and confirmed significant upregulation of the ALDH isoform ALDH1A3 in all histological subtypes of testicular tumors." (PMID 31443351, 2019).
tongue leukoplakia (1 paper, 2015). "ALDH1A3 mRNA and protein levels are greater in advanced stage human HNSCCs than in normal tissue, but there have been no reports of the transcript and protein levels of ALDH1A3 in human tongue leukoplakia." (PMID 26110572, 2015).
viral infections (1 paper, 2020). "There is not any experimental evidence about the regulation of this gene in viral infections but it is shown that ALDH1A3 regulates 2 matricellular proteins (TNC1 and ESM1) in vascular smooth muscle cell proliferation." (PMID 32595353, 2020).
cancer (164 papers, 2005 to 2026). A tumor composed of atypical neoplastic, often pleomorphic cells that invade other tissues. "We recently identified a specific aggressive PDAC subtype marked by elevated expression of the cancer stem cell marker aldehyde dehydrogenase 1 family member A3 (ALDH1A3), which is associated with adverse prognosis in various cancers." (PMID 40781158, 2025). "Aldehyde dehydrogenase 1a3 (ALDH1A3) activity is recognized as a pathogenic trait in cardiometabolic diseases and cancer, though the mechanisms by which ALDH1A3 promotes disease are unclear and effective therapeutic inhibitors of ALDH1A3 are lacking." (PMID 41210994, 2025). "These factors include aldehyde dehydrogenase 1A3 (ALDH1A3), a cancer‐promoting enzyme associated with cancer stem cells, poor prognosis, and the more aggressive triple‐negative breast cancer (TNBC) subtype." (PMID 37753740, 2024). "We also confirmed that ALDH1A3 negatively correlates with clinical parameters associated with cancer aggressiveness, such as pathological tumor stage, Gleason score and tumor size." (PMID 38169509, 2024). "Gene Set Enrichment Analysis (GSEA) 17 confirmed that genes downregulated after the knockdown of both ALDH1A1 and ALDH1A3 were enriched in the datasets associated with normal stem cells, tumor progenitors and poorly differentiated cancer." (PMID 38169509, 2024). "An analysis of the cancer genome atlas (TCGA) database involving 84 PM patients revealed that high ALDH1A3 expression is significantly associated with poorer prognosis." (PMID 39001459, 2024). "Given that metastasis is the primary cause of cancer mortality it is critical to characterize pathways and factors that promote metastasis and therefore focus our investigation on understanding ALDH1A3‐mediated invasion and metastasis." (PMID 37753740, 2024). "Gene amplification was consistently the most reported ALDH1A3 mutation, and this would lead to increased levels of ALDH1A3 in those cancers." (PMID 36672441, 2023). "A few studies indicate a link between ALDH1A3 and the “Warburg effect”, where glycometabolism predominates in the tumor or cancer cells and is associated with ALDH1A3 and cancer progression." (PMID 36672441, 2023). "Consistent with ALDH1A3 association with CSCs, ALDH1A3 expression in cancer is generally associated with worse outcomes, progressive disease, and recurrence." (PMID 36672441, 2023). "The association of ALDH1A3 with CSCs in multiple cancers implies its importance to cancer progression and aggressiveness." (PMID 36672441, 2023). "ALDH1A3-associated chemotherapy resistance across cancer types is consistent with its general importance in tumor progression and associations with CSCs and worse prognosis." (PMID 36672441, 2023). "Accumulating evidence has demonstrated that ALDH1A3 is closely associated with development, progression, radioresistance and prognosis in a variety of cancers." (PMID 36996494, 2023). "Gpr125+ cells at the distal tips of pubertal ducts express particularly high levels of genes, such as Sox 11, Aldh1a3, and Lrfn5, associated with stemness, neurite outgrowth, and cancer, respectively." (PMID 35302059, 2022). "Cytosolic ALDH1A enzymes, and specifically the ALDH1A3 isoform, are good markers of cancer stem cells and have been implicated in carcinogenesis, chemoresistance and relapse." (PMID 35418200, 2022). "Previous clinical studies highlighted the high expression of ALDH1A3 in cancer stem cells (CSCs) correlated to a higher risk of cancer relapses, chemoresistance and a poor clinical outcome." (PMID 33478031, 2021). "Overexpressing ALDH1A3 is associated with cancer stem cell characteristics by increasing cancer cell proliferation." (PMID 32111066, 2020). "Hypermethylation of ALDH1A3 promoter region was found to be one of the underlying mechanisms in some cancers." (PMID 32111066, 2020). "Along with important roles of ALDH1A3 in cancer and cancer stem cells, its underlying regulatory mechanism has become of interest." (PMID 32680476, 2020).